TNF (tumor necrosis factor)
Diseases named in the same sentence as TNF in open-access papers (continued):
Sharing a sentence is not in itself a finding about the gene and the disease.
colitis (continued). "Their exposures also increased TNF-α and IL-6 expression and NF-κB+/Iba1+ cell population in the colon and Proteobacteria population in the gut microbiota, leading to colitis and gut microbiota perturbation." (PMID 33731795, 2021). "These include reductions in colitis symptoms, pro-inflammatory markers TNF-α, IL-1β, IL-6, MPO, and PGE2, and levels of NO and MDA, whereas TGF-β expression, GSH levels, and enzyme activities of SOD, CAT, GPx, and GR, were increased." (PMID 34073220, 2021). "The results showed that ARS treatment notably downregulated the mRNA and protein expression of IL-1β, IL-6, TNF-α, and the protein ratio of p-p65/p65 and p-IκBα/IκBα in colon tissues in colitis mice (p < 0.01)." (PMID 33767628, 2021). "In a rat model of acetic acid ulcerative colitis, this chalcone inhibited the severity of colonic inflammation through downregulating TNF, iNOS and NF-κB signaling." (PMID 33947113, 2021). "YST from low dose to high dose gradually decreased the levels of TNF-α, IL-1β, and IL-6 in colon tissues of colitis mice." (PMID 34055024, 2021). "Our results found that BL down-regulated the expressions of IL-1β, IL-6, and TNF-α inflammatory factors in the colon tissue of colitis mice and increased the expression levels of anti-inflammatory factors IL-10 and TGF-β." (PMID 33954162, 2021). "TNF-α and IL-1β are potent inflammatory mediators, production of which is remarkably increased in the colon tissue of patients with colitis." (PMID 33995942, 2021). "We assessed the role of TNFα in mediating neuronal hyperexcitability during colitis by administering neutralizing α-TNFα antibody intraperitoneally from days 6 to 14 following DSS colitis induction." (PMID 34511110, 2021). "Results demonstrated that feeding BLIDF markedly mitigated DSS-induced acute colitis symptoms and down-regulated IL-6, TNF-α, and IL-1β levels in the colon and serum of colitis mice." (PMID 33807544, 2021). "UAMC-00050 treatment also significantly decreased protein levels of TNF-α, IL-1β, IL-6 and IL-17 present in the colons of the colitis animals." (PMID 34248633, 2021). "The transplantation of FBp, FBi, or FN mitigated IS-induced colitis in mice: they alleviated IS-induced myeloperoxidase and TNF-α and IL-6 expression in the colon." (PMID 33731795, 2021). "The KEGG pathway analysis indicated that the T-cell receptor signalling pathway and TNF signalling pathway were involved in the anti-colitis mechanisms of CSF." (PMID 35010997, 2021). "The results showed that in mice with colitis, EBN improved symptoms of colitis, reduced colonic injury, and inhibited the increases in the levels of the pro-inflammatory cytokines IL-1β and TNF-α." (PMID 33967768, 2021). "In other colitis mouse models, TNF-α, IL-6, and IL-1β in serum and colon were reduced after administering doenjang, fermented soybean paste, and isoflavones such as daidzein and genistein, which are bioactive compounds of soybeans." (PMID 34066160, 2021). "In vagotomized mice a more severe form of inflammation developed after DSS-induced colitis, which was associated with increased levels of IL-1β, IL6, TNFα, and NF-κB levels." (PMID 33562721, 2021). "The underlying mechanisms of the ameliorative effect of chrysophanol on TNF-α stimulated colonic inflammation were elucidated." (PMID 33802855, 2021). "TAK-242 treatment during DSS colitis significantly reduced levels of pro-inflammatory and pro-tumorigenic TNF-α and IL-1β in the colon." (PMID 34025672, 2021). "In previous studies on salt and colitis in mice, high salt showed an increased expression of IL-1β and TNF-α in the colon." (PMID 34066160, 2021). "In parallel, our findings showed a reduction of TNF and an increase in the anti-inflammatory cytokine IL-10 in the colonic tissues from animals with colitis, treated with FA5 or acadesine." (PMID 34199160, 2021).
colitis (continued). "We found that the purified form, B-FAHF-2, significantly suppressed the production of TNF-α by PBMCs and intestinal mucosal from pediatric subjects with CD and abrogated colitis in a murine model at a much lower dose than FAHF-2." (PMID 34926527, 2021). "For IL-2 and LIF, inflammation-induced increases were reversed with an A genotype, whereas for MCP-1 and TNF, colitis-induced increases were attenuated with an A genotype." (PMID 34916909, 2021). "Studies have shown that the abundance of intestinal Clostridium XI is significantly increased, accompanied by decreased gene expression of TNF-α and a decreased inflammation index in the colon after treatment with probiotics in a colitis mouse model." (PMID 34746321, 2021). "For conducting these studies, we established a cellular model of colitis by stimulating CACO2 cells with TNF-α." (PMID 33967625, 2021). "Further, colitis induced lipid peroxidation, neutrophil infiltration, and expression of pro-inflammatory cytokines (IL-1β and TNF-α) decreased in both models." (PMID 34067499, 2021). "By contrast, production of IL-6 was downregulated in macrophages after resveratrol treatment whereas in mice with Dextran Sodium Sulfate (DSS)-induced colitis resveratrol decreased IL-6 release but increased TNF-α release." (PMID 33935732, 2021). "DHPP treatment improved DSS-induced colitis symptoms in rats and lowered the expression of IL-1β, IL-8, and TNF-α." (PMID 34073220, 2021). "In another study, scFvs were used to treat dextran sulphate sodium-induced colitis in mice, whereby introduction of bacteria expressing anti-TNF scFv into mice via gavage led to mucosal delivery of the scFv and subsequent alleviation of colitis." (PMID 34930213, 2021). "Another immunosuppressive treatment was necessary in 10% of cases overall (mostly TNF-alpha inhibitors for colitis)." (PMID 34068892, 2021). "To determine the mechanism by which neutrophils contribute to colitis-induced neuronal hyperexcitability, we evaluated their production of TNFα, which is known to enhance excitability." (PMID 34511110, 2021). "The findings highlight that Otostegia fruticosa protects the severity and extent of colitis in rats by controlling the release of TNF-α and IL-6 as well as the antioxidant effect that resulted in mucosal protective effects." (PMID 33802553, 2021). "Nelumal A also prevented mucosal ulcer development and reduced the expression levels of TNF-α in the colonic mucosa in both DSS-induced colitis and AOM/DSS-induced tumourigenesis models." (PMID 33436792, 2021). "Studies have reported that IL-6 and TNF-α levels are significantly increased in mice with DSS-induced colitis and that these components are involved in the regulation of signaling pathways such as apoptosis, migration, and protein synthesis." (PMID 34901119, 2021). "Compared with the mice in the sham group, an ELISA revealed that pro-inflammatory cytokine levels, including those of TNF-α, IL-1β, and IL-6, increased significantly in the murine model of colitis." (PMID 34594215, 2021). "Studies have shown that systemic TNF-α level is elevated in DSS-induced colitis and in IBD patients." (PMID 33995396, 2021). "The TNF-α concentration (pg/mL) was found to be significantly (p < 0.001) increased in the AA-induced colitis group." (PMID 33802553, 2021). "Levels of the pro-inflammatory cytokines IL-6 and tumor necrosis factor alpha (TNF-α) were higher in mice harboring P. intestinalis on day 7 of DSS colitis." (PMID 32433514, 2021). "Colitis-induced neuronal hyperexcitability was ameliorated by neutrophil depletion or TNFα blockade." (PMID 34511110, 2021). "When human colon cancer cells were xenografted into these mice, the prophylactic blockade of TNFα improved the colitis and the tumors were retained." (PMID 33571254, 2021). "In vivo, acute colitis induced by DSS significantly increased TNF-α secretion in colon tissue in comparison to untreated controls." (PMID 34069671, 2021).
colitis (continued). "These authors reported that NPs releasing Map4k4 siRNA ameliorated colitis in mice via inhibition of the LPS-induced expression of TNFα and IL-1." (PMID 34575416, 2021). "In contrast, in plasma, colitis-induced increases in interleukin (IL)-2, leukemia inhibitory factor (LIF), monocyte chemoattractant protein (MCP)-1, and tumor necrosis factor (TNF) were reduced in animals with an A allele." (PMID 34916909, 2021). "The administration of certain vitamin E derivatives to animals with experimental colitis decreases colonic injury, intestinal neutrophil infiltration, and TNFα levels, and regulates levels of interleukins." (PMID 33499140, 2021). "Some species of Lactobacillus can inhibit colonization of pathogens and lower the expression of TNF-α in a rat colitis model." (PMID 34957184, 2021). "Of note, no benefit was observed in two cases of grade 3 hepatitis and grade 3 colitis treated with anti-TNF-α, thus requiring further immunosuppression." (PMID 34208218, 2021). "It was reported that curcumin and semibionic extraction of compound turmeric can inhibit the proinflammatory signaling by STAT3 and TNF-α in experimental colitis." (PMID 34221084, 2021). "In murine models of experimental colitis, TNF signaling increased MLCK expression, resulting in tight junction dysregulation and barrier loss in the IEC compartment." (PMID 33435303, 2021). "Curcumin has exhibited promising therapeutic effects in a dextran sulfate sodium (DSS)-induced colitis mouse model by obstructing the p38MAPK activity, decreasing the proinflammatory cytokines (i.e., TNF-α) production, and neutrophil infiltration." (PMID 33918207, 2021). "Low Tnf-α mRNA expressions in the rectal tissues of these AMSC-treated rats with colitis coincide with our data showing low TNF-α protein concentrations in blood of AMSC-treated GVHD mice in vivo and mitogen-stimulated PBMC in vitro." (PMID 33510297, 2021). "Recent studies have revealed that blocking of TNF-α activity results in the reduction of inflammation in the colon in both experimental colitis model and patients with ulcerative colitis." (PMID 34745922, 2021). "LPS treatment increased neuroinflammation and colitis with the induction of TNF-α and IL-1β expression in the colon and hippocampus." (PMID 34579150, 2021). "In particular, Kyna suppressed anti-inflammatory IL10 and contributed to colitis in mice, but attenuated the TNF-α expression in human mononuclear cells activated by heat-inactivated Staphylococcus aureus." (PMID 34948292, 2021). "Our studies are in alignment with a study where albendazole enhanced anti-inflammatory effect of TNF blockade in a mouse colitis model; however, the authors showed that the effect was primarily via induction of regulatory macrophages and not via T cells." (PMID 34075120, 2021). "After 7 days, rats with colitis had a significantly higher Il-12 level and a lower TNF-α protein level than those observed in control animals." (PMID 33923129, 2021). "We found that apoptosis, ROS levels, and inflammation were all significantly enhanced in the TNF-α-induced colitis model cells." (PMID 33967625, 2021). "In the colitis rat model, aloin can reduce the inflammatory injury of rats by down-regulating the expression of TNF-α and IL-6." (PMID 34769051, 2021). "Surprisingly, we did not observe any difference in the reduction of intestinal inflammation based on TNFα relative gene expression in colonized animals with colitis (HAC and HC) in comparison to the other groups." (PMID 33499240, 2021). "Inflammatory response plays a key role in activating the production of mature IL-6, IL-1β, and TNF-α in UC patients and colitis mice." (PMID 34867926, 2021). "On the other hand, high expression of TNF-α in activated MCs plays an instrumental role is the pathogenesis of colitis in mice." (PMID 34557187, 2021).
colitis (continued). "On quantitative TNF-α-targeted ultrasound images, a greater signal intensity was observed in the mouse colons with colitis ([1.96 ± 0.45] × 106 a.u.)compared to that of the controls ([0.56 ± 0.21] × 106 a.u., P < 0.001)." (PMID 34556023, 2021). "TKNs loaded with TNFα siRNA resulted in a successful treatment for intestinal inflammation in a murine colitis model." (PMID 34575416, 2021). "A further study showed that TpH2−/− mice with DSS-induced colitis had increased severity of disease characterized by an increased secretion of the pro-inflammatory cytokines IL-1β, IL-6 and, TNF-α, and high mortality rates in comparison to the wild type." (PMID 34502396, 2021). "This is further supported by evidence showing that anti-tumor necrosis factor (TNF) therapies reduce IEC apoptosis in models of colitis and CD patients." (PMID 34075172, 2021). "A study has reported that TNF-α levels, which increase with the development of colonic inflammation, decreased after administration of EA." (PMID 34586188, 2021). "Exposure to RS led to colon shortening, induced myeloperoxidase activity and NF-κB activation (p-p65 to p65 ratio), and increased TNF-α and IL-6 expression in the colon, leading to the outbreak of colitis." (PMID 34391441, 2021). "Our results showed the expression levels of pIκB, NFκB p65 (phospho S536), IL-1β, IL-6 and TNF-α were increased in colitis mice." (PMID 34456904, 2021). "In the current study, we successfully established both a DSS-induced rat model of colitis and a TNF-α-induced cellular model of colitis." (PMID 33967625, 2021). "In fact, different publications have shown the positive effect of TNF inhibition on experimental induced murine colitis." (PMID 33435303, 2021). "In cases of steroid-refractory irAEs like colitis, pneumonitis, arthritis, and hepatitis, other immunomodulatory treatments such as blocking antibodies against tumor necrosis factor alpha (TNF-α) or interleukin 6 (IL6) were shown to be effective." (PMID 34208218, 2021). "In the CD40-induced colitis model, BsAbs target IL-23 and TNF-α shows a synergistic effect relative to antibodies against TNF-α and IL-23 alone in inflammatory bowel disease." (PMID 34025638, 2021). "The latest experimental and clinical data show that pro-inflammatory cytokines such as TNF-α, IL-1β and IL-6 play an important role in the pathogenesis of colitis." (PMID 34551815, 2021). "The patients with IBD-like colitis were treated with mesalazine (n = 8), azathioprine (n = 2), methotrexate (n = 2), steroids (n = 2), or anti-TNFα (n = 4) according to the IBD treatment guidelines." (PMID 34456911, 2021). "Exposure to EC significantly induced colitis in mice: it induced colon shortening, myeloperoxidase activity, and TNF-α, IL-1β, and IL-6 expression in the colon." (PMID 33731795, 2021). "A typical example is that the colitis developed in IL-10 mutant mice are refractory to anti-TNF-α therapy." (PMID 34746207, 2021). "The colitis-characterized pro-inflammatory cytokines such as TNF-α secreted by epithelial layer cells and IL-1β of colon homogenate were significantly decreased in rTsPmy-treated mice in comparison to PBS-treated mice." (PMID 34336843, 2021). "In rats with drug-induced colitis, canthin-6-one 1 reduced the production of pro-inflammatory mediators TNF-α (tumor necrosis factor α), IL-1β (interleukin-1β), IL-12p70 (interleukin-12p70), and VEGF (vascular endothelial growth factor)." (PMID 34299599, 2021). "A previous study suggested that Cinacalcet can be used as an add-on therapy for IBD to reduce production of the cytokines interferon-γ, IL-1α, and TNFα in the colon of dextran sulfate sodium (DSS)-induced colitis BALB/c mice." (PMID 34880751, 2021). "Here, we show that secretion of luminal glycoprotein 2 (GP2) from pancreatic acinar cells is induced in a TNF–dependent manner in mice with chemically induced colitis." (PMID 33594081, 2021).
colitis (continued). "Butyricicoccus strain B. pullicaecorum was able to attenuate chemically induced colitis through the downregulation of TNFα." (PMID 34531862, 2021). "We successfully established a rat model of dextran sulfate sodium- (DSS-) induced colitis as well as a cellular model of TNF-α-induced colitis." (PMID 33967625, 2021). "Pretreatment of rats with telmisartan reduced TNBS-induced colitis decreased the disease severity and suppressed the inflammatory response by attenuating the function of TNF-α, prostaglandin E2, and Myeloperoxidase and restoring IL-10." (PMID 33628160, 2021). "Treatment with alliin in DSS-induced colitis mice reduced colon damage, showing a decrease in pro-inflammatory cytokines (IL-6, IL-1β, and TNF-α) in colonic tissue." (PMID 34068714, 2021). "The TNF-α-treated Caco-2 cell model and mouse colitis model induced by dextran sulfate sodium (DSS) or 2,4,6-trinitrobenzenesulfonic acid (TNBS) were established and employed." (PMID 33776781, 2021). "Intraperitoneal injection of LPS induced colitis: it induced colon shortening, IL-1β, IL-6, and TNF-α expression and suppressed IL-10 expression in the colon." (PMID 33985438, 2021). "TNFα siRNA demonstrated an effective activity to drastically reduce the TNFα expression and promoted anti-inflammatory effects in vitro and ex vivo leading to colitis attenuation in a dextran sodium sulfate (DSS)-induced colitis mouse model." (PMID 34575416, 2021). "Apple polyphenols ameliorated DSS colitis and dampened the expression of proinflammatory transcripts, such as IL-6, IL-17, IL-22, and TNF-α." (PMID 33299531, 2020). "Pretreatment of colitis mice with L. reuteri I5007 significantly reduced the DSS-induced production of TNF-α, IL-6, IFN-γ, and IL-17A, as well as increased the level of IL-10 compared with the DSS group." (PMID 32751784, 2020). "Similar results were seen in two other studies examining the effects of Vitamin D analogs, ZK191784 and TX527, on TNF-α expression in DSS-induced colitis murine models." (PMID 32422882, 2020). "RG and fRG also alleviated the EC- or IS-induced colitis in mice; they suppressed the EC-induced myeloperoxidase activity, NF-κB activation, and TNF-α and IL-6 expression, and NF-κB+/CD11c+ cell population in the colon." (PMID 32224881, 2020). "Mice treated with vitamin D in a DSS-induced colitis model showed significantly reduced TNF-α expression compared to the control group." (PMID 32422882, 2020). "In TNBS-induced murine colitis, silymarin, has been shown to rebalance inflammatory cytokines such as TNF-α, IL-1β, and IL-6." (PMID 32486445, 2020). "Recently, nicotine was shown to cause a decrease in leukocyte recruitment, disease activity index (DAI), and histological score in DSS colitis and block TNF-mediated expression of mucosal vascular addresin cell adhesion molecule-1 in endothelial cells." (PMID 32855621, 2020). "As TNBS-induced colitis model promotes a Th1 response, we expected a more marked increase in the TNF-α." (PMID 32183497, 2020). "Literature studies have shown that a wide variety of agents in the treatment of colitis such as ozone, dexpanthenol, nesfatin-1, ilioprost, and anti-TNF have been tried and demonstrated in experimental studies." (PMID 32555936, 2020). "This anti-inflammatory cytokine is important in suppressing IFN-γ and TNF-α by limiting macrophage activity, the production of which in mice was shown to be promoted by Bacteroides fragilis to inhibit colitis through the suppression of IL-17a production." (PMID 32670220, 2020). "Remarkably, all measures assessed showed that Divertin was superior or equivalent to anti-TNF in limiting T cell transfer colitis severity." (PMID 32028590, 2020). "TNF-α plays a pivotal role in triggering the accumulation and activation of leukocytes in colitis and hence is an important therapeutic target." (PMID 32067099, 2020). "Shaoyao decoction decreases the expression of TNF-α, IL-1β, and IL-6 in DSS-induced colitis-associated CRC." (PMID 32565784, 2020).